ZNF607 (zinc finger protein 607)
Description:
May be involved in transcriptional regulation.
Synonyms: MGC13071; FLJ14802
Tractability: PROTAC: ubiquitination databases record sites on it.
Gene: Protein-coding gene on chromosome 19 (37,696,363 to 37,719,775, reverse strand). Ensembl gene ENSG00000198182.
Subcellular location: Nucleus
Subcellular location (Human Protein Atlas): Nucleoplasm
Pathways (Reactome):
Gene expression (Transcription): Generic Transcription Pathway
Gene Ontology:
Molecular function: protein binding; DNA-binding transcription factor activity, RNA polymerase II-specific; RNA polymerase II cis-regulatory region sequence-specific DNA binding; DNA binding
Biological process: regulation of transcription by RNA polymerase II; regulation of DNA-templated transcription
Cellular component: nucleus
Genetic constraint (gnomAD): Loss-of-function variants: 5 observed, 10.89 expected, observed/expected ratio (o/e) 0.46, 90% interval 0.24 to 0.97. The upper end of that interval is the gene's LOEUF score, 0.97, which puts it in group 4 of 6, group 1 being the genes least tolerant of losing a copy. Missense variants: 841 observed, 888.74 expected, observed/expected ratio (o/e) 0.95, 90% interval 0.89 to 1. Synonymous variants: 282 observed, 287.1 expected, observed/expected ratio (o/e) 0.98, 90% interval 0.89 to 1.08.
Homologues: Orthologues: chimpanzee ZNF607 (99% identical), macaque ZNF607 (96% identical). Paralogues in human: ZNF546 (40% identical), ZNF30 (38% identical), ZNF841 (36% identical), ZNF540 (36% identical), ZNF585B (36% identical), ZNF595 (36% identical), ZNF658 (36% identical), ZNF41 (36% identical), ZNF836 (36% identical), ZNF470 (36% identical), ZNF568 (36% identical), ZFP28 (35% identical), and 164 more.
Diseases named in the same sentence as ZNF607 in open-access papers:
ZNF607 is named in the same sentence as 4 diseases in open-access papers, as found by Europe PMC text mining. Sharing a sentence is not in itself a finding about the gene and the disease. The quoted sentences say what the papers report.
metastatic tumor (1 paper, 2012). "Interestingly, the allelic frequency of K187M in ZNF607, the only somatic variant found in the primary tumor (16.67%) was consistent in the metastatic tumor (15.25%), suggesting that the other 19q mutations occurred later in the tumor evolution." (PMID 22916110, 2012).
sarcoidosis (1 paper, 2025). Sarcoidosis is a multisystemic disorder of unknown cause characterized by the formation of immune granulomas in involved organs. "The most increased proteins in sarcoidosis were uncharacterized protein C6orf132 (Q5T0Z8, log2FC, 1.7 and −log10P, 11) and zinc finger protein 607 (Q96SK3, log2FC, 2.5 and −log10P, 7.0)." (PMID 41279897, 2025).
tumor (2 papers, 2012 to 2021). "Among these mRNAs, TMEM164, ZNF607, and ANKRD13B showed significant altered expression across tumor stages, indicating their role in cancer progression and invasion." (PMID 35140741, 2021).
cancer (1 paper, 2021). A tumor composed of atypical neoplastic, often pleomorphic cells that invade other tissues. "The role of ZNF607 and mainly KDELC1 has not been clearly elucidated in cancers." (PMID 35140741, 2021).